SLF2 (SMC5/6 complex localization factor 2)
Description:
Plays a role in the DNA damage response (DDR) pathway by regulating postreplication repair of UV-damaged DNA and genomic stability maintenance. The SLF1-SLF2 complex acts to link RAD18 with the SMC5-SMC6 complex at replication-coupled interstrand cross-links (ICL) and DNA double-strand breaks (DSBs) sites on chromatin during DNA repair in response to stalled replication forks. Promotes the recruitment of the SMC5-SMC6 complex to DNA lesions. Plays a role in SMC5-SMC6 complex recruitment for viral restriction. Forms a complex with SIMC1 and this complex is required to recruit SMC5-SMC6 complex to PML nuclear bodies and sites of viral replication.
Synonyms: C10orf6; FAM178A; FLJ10512; FLJ25012; hNSE6; ATELS1
Tractability: PROTAC: ubiquitination databases record sites on it.
Gene: Protein-coding gene on chromosome 10 (100,912,963 to 100,965,134, forward strand). Ensembl gene ENSG00000119906.
Subcellular location: Nucleus; Nucleus, PML body
Subcellular location (Human Protein Atlas): Nucleoplasm; Vesicles
Gene Ontology:
Molecular function: protein binding; protein-containing complex binding; ubiquitin protein ligase binding
Biological process: DNA damage response; positive regulation of double-strand break repair; positive regulation of maintenance of mitotic sister chromatid cohesion; positive regulation of protein-containing complex assembly; protein localization to site of double-strand break; chromatin looping; double-strand break repair via homologous recombination; protein sumoylation; regulation of telomere maintenance
Cellular component: chromatin; nucleoplasm; nucleus; PML body; site of double-strand break; chromosome, telomeric region; Smc5-Smc6 complex
Genetic constraint (gnomAD): Loss-of-function variants: 43 observed, 82.53 expected, observed/expected ratio (o/e) 0.52, 90% interval 0.41 to 0.67. The upper end of that interval is the gene's LOEUF score, 0.67, which puts it in group 2 of 6, group 1 being the genes least tolerant of losing a copy. Missense variants: 970 observed, 1,107.8 expected, observed/expected ratio (o/e) 0.88, 90% interval 0.83 to 0.92. Synonymous variants: 377 observed, 394.06 expected, observed/expected ratio (o/e) 0.96, 90% interval 0.88 to 1.04.
Homologues: Orthologues: chimpanzee SLF2 (99% identical), macaque SLF2 (97% identical), dog SLF2 (91% identical), rabbit SLF2 (90% identical), rat Slf2 (85% identical), mouse Slf2 (84% identical), pig SLF2 (84% identical), guinea pig SLF2 (81% identical), tropical clawed frog slf2 (28% identical), zebrafish slf2 (20% identical). Paralogues in human: FAM178B (15% identical).
Diseases named in the same sentence as SLF2 in open-access papers:
SLF2 is named in the same sentence as 13 diseases in open-access papers, as found by Europe PMC text mining. Sharing a sentence is not in itself a finding about the gene and the disease. The quoted sentences say what the papers report.
anemia (2 papers, 2022 to 2023). A reduction in the number of red blood cells, the amount of hemoglobin, and/or the volume of packed red blood cells. "A recent report of 11 patients with variants in SMC5 and SLF2 (SMC5-SMC6 complex localization factor 2) displayed microcephaly, anemia, short stature, and cardiac defects." (PMID 38203602, 2023). "Here, the authors identify mutations in SLF2 and SMC5 as cause of Atelís Syndrome characterized by microcephaly, short stature, anemia, segmented chromosomes and mosaic variegated hyperploidy." (PMID 36333305, 2022). "Collectively, these clinical and genetic observations support the premise that variants in SLF2 and SMC5 cause microcephaly and short stature associated with cardiac defects and the development of anemia." (PMID 36333305, 2022). "In addition to reduced brain size, NDD, and CHD, patients with variants in SLF2 or SMC5 were found to have ocular abnormalities, growth restriction, anemia, and skin hyperpigmentation, a condition recently named Atelis syndrome." (PMID 38203602, 2023). "Here we report the clinical and genetic characterization of 11 patients with biallelic variants in two components of the newly described RAD18-SLF1/2-SMC5/6 DDR pathway, SLF2 and SMC5, exhibiting microcephaly, short stature, cardiac defects and anemia." (PMID 36333305, 2022). "Here, we identify biallelic variants in two components of the RAD18-SLF1/2-SMC5/6 genome stability pathway, SLF2 and SMC5, in 11 patients with microcephaly, short stature, cardiac abnormalities and anemia." (PMID 36333305, 2022).
microcephaly (2 papers, 2022 to 2023). A congenital or acquired developmental disorder in which the circumference of the head is smaller than normal for the person's age and sex. "Consistent with our observations from F0 embryos injected with sgRNA and Cas9, stable F2 slf2 null mutants also exhibited microcephaly and aberrant craniofacial patterning." (PMID 36333305, 2022). "In vivo ablation of slf2 and smc5 in zebrafish recapitulate patient phenotypes including microcephaly and craniofacial patterning defects, likely due to concomitant cell cycle defects and apoptosis." (PMID 36333305, 2022).
B‐cell lymphoma (1 paper, 2023). "Starting from an unbiased screening approach, we identified the SMC5‐SMC6 Complex Localization Factor 2 (SLF2) as a regulator of the DDR and biomarker for a B‐cell lymphoma (BCL) patient subgroup with an adverse prognosis." (PMID 37485814, 2023).
Fanconi anemia (1 paper, 2023). Fanconi anemia (FA) is a hereditary DNA repair disorder characterized by progressive pancytopenia with bone marrow failure, variable congenital malformations and predisposition to develop hematological or solid tumors. "Another group of proteins, whose chromatin association was affected upon SLF2 loss belongs to regulators of DDR, such as components of the Fanconi anemia repair pathway and the RAD51‐mediated HR machinery." (PMID 37485814, 2023).
lymphoma (1 paper, 2023). A malignant (clonal) proliferation of B- lymphocytes or T- lymphocytes which involves the lymph nodes, bone marrow and/or extranodal sites. "Pathways mediating the DDR are often impaired during tumorigenesis and we identified altered DDR in SLF2‐deficient lymphomas." (PMID 37485814, 2023). "While depletion of SLF2 did not affect the sensitivity to SUMOi in non‐cancer cell lines, we could validate the synthetic lethality driven by SLF2 loss in DLBCL in OCI‐Ly19 SLF2KO lymphoma cells (Dataset EV1)." (PMID 37485814, 2023). "Moreover, low SLF2 expression is associated with adverse prognosis in DLBCL patients and reduced sensitivity to a standard lymphoma drug." (PMID 37485814, 2023). "Transduced (GFP+) SLF2 KO lymphoma cells were transcriptome profiled." (PMID 37485814, 2023). "Moreover, we detected insertions and deletions (InDels) in Slf2‐sgRNA lymphomas, indicating efficient on‐target gene editing." (PMID 37485814, 2023). "Importantly, our work establishes SLF2 as a highly conserved and actionable tumor suppressor and we propose a treatment strategy for a subgroup of aggressive lymphoma patients with adverse prognosis defined by a low SLF2 state." (PMID 37485814, 2023). "To test this putative vulnerability caused by SLF2 deficiency and altered SUMOylation, we investigated the efficacy of a first‐in‐class small‐molecule inhibitor of SUMOylation (SUMOi), TAK‐981/subasumstat, which is tested in clinical phase I/II trials in lymphoma patients (NCT03648372)." (PMID 37485814, 2023). "Together, our results identify SLF2 as a DDR regulator and reveal co‐targeting of the DDR and SUMOylation as a promising strategy for treating aggressive lymphoma." (PMID 37485814, 2023). "Depletion of SLF2 in murine lymphoma cell lines derived from primary Eμ‐myc lymphomas resulted in the compromised activation of CHK1, thus revealing a highly conserved mechanism regulating the CHK1 axis by SLF2." (PMID 37485814, 2023).
Seckel syndrome (1 paper, 2022). A rare autosomal recessive inherited syndrome caused by mutations in the ATR gene, RBBP8 gene, CENPJ gene, CEP152 gene, CEP63 gene, NIN gene, DNA2 gene, or TRAIP gene. "All SLF2 and SMC5 mutant LCLs examined exhibited a significant increase in spontaneous replication fork stalling and fork asymmetry comparable to that observed in an LCL derived from an ATR-Seckel Syndrome patient." (PMID 36333305, 2022).
cancer (2 papers, 2023 to 2025). A tumor composed of atypical neoplastic, often pleomorphic cells that invade other tissues. "Of note, we also show experimentally that SLF2 loss leads to impaired CHK1 activation in response to DNA damage stress in non‐hematopoietic cancer cells and thus provide a mechanistic framework and identify a molecular vulnerability for a highly conserved feature of aggressive cancers." (PMID 37485814, 2023). "We link SLF2 deficiency to a defective DDR and establish co‐targeting of the DDR and SUMOylation as a treatment strategy for various aggressive human cancers, including DLBCL." (PMID 37485814, 2023). "In summary, we here identified SLF2 as a previously unappreciated cancer gene involved in the DDR." (PMID 37485814, 2023). "SLF2 has no known function in cancer yet has been identified as a DNA repair factor that acts as a localization factor of the SMC5/6 complex and other DNA damage and DNA repair factors at DNA damage sites." (PMID 37485814, 2023).
infection (1 paper, 2023). The state of being infected such as from the introduction of a foreign agent such as serum, vaccine, antigenic substance or organism. "Furthermore, in our studies of HBV-ΔX infection of HepG2-NTCP cells with inducible HBx expression, preformed cccDNA can be recognized and directed to PML bodies in the presence of SMC5/6 and SLF2." (PMID 37338350, 2023).
neurodevelopmental disorder (1 paper, 2022). A behavioral and cognitive disorder with onset during the developmental period that involves impaired or aberrant development of intellectual, motor, or social functions. "Here, we report 11 patients with a neurodevelopmental disorder overlapping clinically with MVA and Fanconi Anemia (FA) with pathogenic variants in SLF2 and SMC5, two components of the recently discovered RAD18-SLF1/2-SMC5/6 genome stability pathway." (PMID 36333305, 2022).
tumor (1 paper, 2023). "Considering the tumor‐relevant molecular mechanism downstream of SLF2 loss, we identified loss of CLSPN." (PMID 37485814, 2023). "Thus, we here conclude that SLF2 is a tumor suppressor gene in mice, and link SLF2 loss to an impaired DDR in BCLs." (PMID 37485814, 2023). "Together, these findings indicate a mechanism by which CLSPN loss subsequent to SLF2 deficiency may explain the tumor suppressor function of SLF2, while SLF2 also acts as a regulator of several factors involved in cell cycle progression and DNA repair." (PMID 37485814, 2023). "Consequently, loss of SLF2 led to a striking acceleration and penetrance of B‐cell lymphomagenesis in vivo, thus validating SLF2 as a functionally relevant tumor suppressor gene." (PMID 37485814, 2023). "SLF2 was identified as a tumor suppressor of B‐cell lymphomagenesis and a crucial regulator of CHK1, and its deficiency was associated with defective DNA damage response and synthetic lethality to SUMOylation inhibition." (PMID 37485814, 2023). "As a result, we identified SLF2 loss as a biomarker for a subgroup of human DLBCL patients with adverse prognosis and provided direct experimental evidence that SLF2 acts as tumor suppressor." (PMID 37485814, 2023). "Here, we identify SLF2 as a tumor suppressor of B‐cell lymphomagenesis and a crucial regulator of the CHK1 axis." (PMID 37485814, 2023). "To validate the functional role of SLF2 loss for restricting B‐cell lymphomagenesis in vivo, we next applied a CRISPR/Cas9 in vivo platform for the validation of tumor suppressor genes." (PMID 37485814, 2023). "Together, these data identify SLF2 as a functionally relevant tumor suppressor in murine and human BCL." (PMID 37485814, 2023). "In line with the commonly accepted note that an activated DDR is considered a barrier for malignant transformation, the transposon insertion pattern of the candidate Slf2 was characterized by scattered and bi‐directional insertions, revealing that Slf2 may act as a tumor suppressor gene." (PMID 37485814, 2023). "Tumor cells lacking SLF2 are characterized by a high level of DNA damage, which leads to alterations of the post‐translational SUMOylation pathway as a safeguard." (PMID 37485814, 2023).
SLF2 also shares sentences with these, for which no sentence is quoted: Atelís Syndrome (2 papers); breast carcinoma (1); Promyelocytic Leukemia (1).